ISG15 (ISG15 ubiquitin like modifier)
Diseases named in the same sentence as ISG15 in open-access papers (continued):
Sharing a sentence is not in itself a finding about the gene and the disease.
infection (continued). "At 6 h post-infection, the expression levels of IFN1, ISG15, and Mx in rVHSV-P-infected cells were lower than those in rVHSV-wild-infected cells." (PMID 33465148, 2021). "Inconsistent with the observed trend in the IFNB1 level, persistent upregulation of numerous ISGs, including CXCL10, MX1, and ISG15, was observed in response to SARS-CoV-2 infection from 3 to 7 days post-infection." (PMID 34104087, 2021). "Compared to uninfected cells, the transcriptional response to infection including IFNβ, RIG-1, MDA-5, ISG15, and OASL was increased at 48 hpi, with IFNβ and OASL expression further increased following phenelzine treatment." (PMID 34031383, 2021). "There was higher expression of IFN-β, IFIT1, IFIT3, ISG15, and IRF7 mRNA in A549 XRN1 KO cells after 8 h of infection with various virus strains, including WSN (H1N1), PR8 (H1N1), CA04 (H1N1), and HK4801 (H3N2)." (PMID 34311580, 2021). "In this review, we examine the emerging role of ISG15 in antiviral immunity with a particular focus on how HERC5 orchestrates the specific and timely ISGylation of viral proteins in response to infection." (PMID 34207696, 2021). "The principal effect of YTHDF3 depletion on the innate host response to PVSRIPO infection was dampened induction of ISGs (STAT1, MDA5, IFIT1, ISG15, OAS1)." (PMID 33849973, 2021). "At 6 h post-infection, rVHSV-P blocks the induction of IFN1, ISG15, and Mx relative to rVHSV-wild in both HINAE cells and flounder tissues." (PMID 33465148, 2021). "For this, A549 cells transfected with the siRNAs and infected with PR8 as above were harvested at 0 h, 6 h, 12 h and 24 h post-infection, and viperin, IFITM3 and ISG15 polypeptides were detected by western blotting." (PMID 35095845, 2021). "The qRT-PCR analyses showed that IL16 deficiency slightly increased IFN-β and ISG15 expression before PR8 infection, however, dramatically elevated IFN-β and ISG15 expression after PR8 infection." (PMID 34630361, 2021). "Next, to investigate the role of ISG15 in PRRSV infection, PAMs were treated with various serial dilutions of recombinant sISG15 for 12 h prior to the infection with PRRSV-SD16 strain at 1 MOI." (PMID 32927637, 2020). "Intriguingly, following infection with different doses of CSFV (MOI = 0.1, 1, or 3) for 24 h, both mRNA and protein levels of ISG15 were upregulated." (PMID 32093773, 2020). "Both, GMCSF- and FLT3L-BMDCs responded to mOVA2 infection with type I IFN activation signatures, e.g. induction of p-STAT1(Y701), STAT1, TAP1 and ISG15." (PMID 31988324, 2020). "Upon fetal infection, a set of core responsive IFN-inducible genes (CXCL10, IFIH1, IFIT1, IFIT3, ISG15, and MX1) were strongly upregulated in both tissues." (PMID 33148169, 2020). "Previous work has shown that cells from ISG15-deficient patients expressed higher levels of ISGs compared with normal controls when treated with rIFN-α, and these cells were resistant to several viruses; however, it was not clear at what stage of infection viruses were blocked or how." (PMID 32423918, 2020). "After the infection of mice with HSV-1, the expression levels of Ifnb, Ccl5, and Isg15 were significantly lower in the spleens, livers, and lungs of Arrb2−/− mice than in those of WT mice." (PMID 33243993, 2020). "The ubiquitin-like protein (Ubl) ISG15 is strongly induced by IFN and is critical for regulating how cells respond to infection." (PMID 32423918, 2020). "The expression of IFNB1, ISG15, and IFIT1 mRNA were decreased in HEK293 cells transfected with Parkin upon infection with SeV." (PMID 32983119, 2020). "The sC69∗ mutant showed to attenuate host innate immune response during infection and poly (I:C) treatment such as IL29, ISG15, and RIG-I (p < 0.05)." (PMID 31249567, 2019). "The mRNA levels of APOBEC3G, ISG-15, RIG-I, IFN-α, and IFN-β were significantly enhanced in the mice infected with rt269I on 4 days post-infection." (PMID 31402915, 2019).
infection (continued). "SINV infection led to a rapid increase by 4hpi in mRNA for ISGs RIG-I, PKR, MDA-5, with the greatest increase being ISG15 and ISG56 mRNA, which were undetectable before infection." (PMID 31905741, 2019). "To avoid mistakenly identifying ubiquitin or NEDD8 sites as ISG15 sites (due to possible indirect effects of Isg15 deletion or USP18C61A/C61A mutation), we assessed whether ubiquitin and NEDD8 levels appear to vary using SDS-PAGE prior to or following infection." (PMID 31772204, 2019). "According to our results, reduction of ISG15 and USP 18 gene expression in the chronic phase of infection suggested their direct role in virus immunity and importance." (PMID 30949318, 2019). "Although there were differences in induction of some ISGs (IFITM3, IRF3, ISG15, VIG1, and MX1), mRNA levels of type I IFNs were below the detection limit in pLNs or similar in spleens of B6 and CD169−/− mice post-FVC infection." (PMID 30595553, 2019). "BeAn-infected SJL mice express several genes involved in the innate immune responses (Tlr7, Tlr8, Tlr9, Myd88, Isg15, Isg20, Mx1, and IL6) in the spinal cord during the late phase of TMEV-IDD at 165 days post infection." (PMID 30669615, 2019). "Meanwhile, the expression levels of SOCS1, INF-a, ISG15, and ISG56 greatly increased 96 h after DENV-ADE infection." (PMID 29566761, 2018). "We also observed reduced expression of antiviral cytokine IFN-β, ISG15 and MxA after multiple rounds of viral replication in H5N1 compared to H1N1 virus-infected cells at the late stage of infection." (PMID 29475453, 2018). "However, in RoNi cells, higher IFNAR levels, especially soluble IFNAR2—a putative potentiator of quicker more sustained responses—could enable strong IFN-independent, IRF-mediated ISG15 induction, allowing cells to engage a core aspect of the ISGylation pathway in advance of the infection." (PMID 30400182, 2018). "We found that free ISG15 enhances the production of IFN-γ and IL-1β during murine infection with Toxoplasma gondii." (PMID 29891555, 2018). "As expected, HSV-1 ICP0-null mutant infection efficiently induced the transcription (by 8–9 hpi) and expression (by 16 hpi) of three independent ISG products (Mx1, ISG15, and ISG54), a host response that was significantly impaired during WT HSV-1 infection." (PMID 29309427, 2018). "Surprisingly, qRT-PCR analysis demonstrated that only HFt cells induced ISG (Mx1, ISG15, ISG54) expression during HSV-1 ICP0-null mutant infection." (PMID 29309427, 2018). "In this study, we show that free extracellular ISG15 is produced and released in a type I IFN–dependent fashion and enhances IFN-γ and IL-1β levels during infection with live replicative Toxoplasma type II." (PMID 29891555, 2018). "Correspondingly, qRT-PCR demonstrated that the induction of ISGs (Mx1, ISG15, ISG54) was significantly impaired in both IFI16 or PML depleted cells in response to HSV-1 ICP0-null mutant infection at 9 hpi." (PMID 29309427, 2018). "When we measured ROS levels after infection, we found an increase only in ISG15-/- BMDM, indicating that following VACV infection ROS accumulation occurs in ISG15-/- cells." (PMID 29077752, 2017). "We observed approximately 0.5 to 1-log fold greater expression of ISG15, EIF2AK2, OAS1, IFNA4, and IFNB1 in the lungs of rWSN-GH-NS1-Y84F infected mice on days 1 and 3 post-infection compared with the lungs of rWSN-GH-NS1-wt infected mice." (PMID 28498306, 2017). "Nevertheless, a better understanding of how these different processes regulated by ISG15 may affect downstream immune functions in vivo will be required to elucidate the complete role of ISG15 in the generation of protective responses during infection with different pathogens." (PMID 29077752, 2017). "A clear increase in NO production was observed following IFN treatment in ISG15+/+ BMDM, which was maintained after infection." (PMID 29077752, 2017).
infection (continued). "Real-time qRT-PCR results showed that the presence of 200 U/mL IFN-β dramatically increased the mRNA levels of ISG15, OAS1, and MX1 in LC, macrophages, and SC at 8 h post-infection." (PMID 28239382, 2017). "Consistently, deletion of FBXW7 in macrophages also led to decreased expression of ISG15 and ISG20 mRNAs after infection with VSV, H1N1 virus or RSV." (PMID 28287082, 2017). "In non IFN-treated cells, similar respiration levels were observed in ISG15+/+ and ISG15-/- BMDM uninfected or at early times post-infection." (PMID 29077752, 2017). "We found a significant increase in levels of IFN-α and IFN-β, interferon-stimulated genes (ISGs) CXCL-10 and ISG15, and the proinflammatory cytokines interleukin-6 (IL-6) and tumor necrosis factor (TNF) at 16 to 24 hpi following infection with N1040A." (PMID 27965448, 2016). "Four interferon-stimulated proteins with antiviral function were up-regulated only in the Hep-dG infection group, including RIG-I, ISG15, Zc3hav1, and Irgm1." (PMID 26217322, 2015). "In BEAS-2B cells at 10 h of infection, IRF-7, ISG15 and Mx1 expression were significantly down-regulated (p<0.05) while STING expression was significantly up-regulated (p<0.05); expression of IFN-β and IL-6 was unchanged." (PMID 25313647, 2014). "This signature differs from that observed at the onset of the infection, when circulating virus is detectable and type I interferon, IP10, MCP1, ISG15 are highly elevated." (PMID 23556021, 2013). "In the present study, the IFN-stimulated genes (IFIT1, IFIT3, MX1, ISG15, OAS1, and IFI6) were dramatically increased at 16 h and 24 h post infection, which should trigger powerful antiviral functions." (PMID 23527143, 2013). "In summary, VAVC infection appears to be similar in ISG15+/+ and ISG15−/− MEFs, but appears to be reduced in ISG15−/− macrophages, which correlates with lower cell virus-induced death." (PMID 24137104, 2013). "In accord with this, depletion of endogenous Ube1L from the Huh7.25.CD81 cells, as such or after ectopic expression of ISG15, UbcH8 and HERC5, resulted in an increase in IFNβ induction after infection with HCV." (PMID 22022264, 2011). "During VVΔE3L infection high levels of TNF-α, IFN-β, IFN-α, IL-6 and ISG15 mRNA were detected, which is in accordance with previous publications." (PMID 22174864, 2011). "By 2 days post-infection, just prior to when the majority of ISG15−/− mice succumb to infection, we still detected similar viral loads between WT, UbE1L−/− and ISG15−/− mice in the analyzed tissues." (PMID 22028657, 2011). "Though NFkB, IRF7 and IRF3 silencing decreased ISG15 expression, only IRF7 decreased the level of the reporter gene expression by more than 50% and partially reverted the resistance to infection with Ad5GFP." (PMID 20113473, 2010). "It should be noted that there is an increase in the conjugation of ISG15 to its target proteins after VVΔE3L, but reduced in levels after MVA infection." (PMID 18604270, 2008). "In addition, perturbation of Hrf-063 or eIF4A1 altered the expression of STAT1 and CAV1, and Hrf-063 regulated ISG15 and STING1 transcription in a time- and infection-dependent manner." (PMID 42306525, 2026). "The basal levels of IFN-γ were found to be comparable between WT and ISG15−/− mice in the absence of infection." (PMID 40627782, 2025). "An interesting observation was that type I IFN induced the expression of ISG15 protein in all cells tested, but significant secretion of ISG15 was only observed in response to infection and not to type I IFN stimulation." (PMID 40627782, 2025). "In mice that lacked ISG15, there were signs of more severe infection and tissue damage, along with less of the anti-inflammatory molecule IL-10." (PMID 40627782, 2025).
infection (continued). "Although there appeared to be overall immunosuppressive changes to gene expression in cells infected in ADE compared to conventional infection conditions, select immune signaling molecules were enriched, including top upregulated DEGs CCR7, ISG15, IL23A, and TRAF." (PMID 39902963, 2025). "Quantitative real-time PCR (qRT-PCR) analysis showed that overexpression of Sec10 significantly attenuated the transcriptional levels of antiviral genes such as Ifn-β, Isg15, Isg54, and Isg56 induced by transfection with poly(I:C) or by vesicular stomatitis virus (VSV) infection." (PMID 40920886, 2025). "Among them, we wanted to analyze the expression of interferon α and β, IFITM3, ISG15, MyD88, and IRF1 in DF-1 and DSK cells upon MVA infection and verify whether their expression is affected when STING functionality is impaired." (PMID 40981440, 2025). "We infected previously characterized A549 RIG-I knockout (ΔRIG-I) and non-targeted (NT) control cells with either a recombinant WT (WT-R) or an E3L deletion mutant of VACV (VACV ΔE3L) and quantified viral titers and mRNA levels of ISG15 and IFN-β at 8 and 16 hours post infection (hpi)." (PMID 40258008, 2025). "This suggests that the robust secretion of ISG15 in primary host cells results from infection, rather than cytokine stimulation." (PMID 40627782, 2025). "Among ISGs, only ISG15 and ISG12(A) were upregulated in all infections at 7 dpi." (PMID 40459260, 2025). "At 24 h post-infection, HMPV boosted ISG15, OAS1, MX1, and IRF7 by multiples of ten magnitudes." (PMID 40732740, 2025). "Several additional immune and inflammatory responses were brought out by poly I:C (e.g., ISG15, CXCL10 and OAS) stimulation, and they correspond to the CJ + SEP transcripts identified here, suggesting a common response to infection by very different cell types." (PMID 40434970, 2025). "Ct infection significantly increased the release of ISG15 in both HUVEC and Fimb cells, but not in HeLa 229 cells." (PMID 40627782, 2025). "The common pathways upregulated upon infection by each of these three viruses included innate antiviral and inflammatory pathways, such as OAS and ISG15-mediated antiviral responses, interferon α/β signaling, cytokine and interleukin signaling, NOD1/2 signaling, and the NLRP3 inflammasome pathway." (PMID 40857262, 2025). "The upregulation of ISG15, CXCL-10, ADAM8, and CSF1 was found after infection with vPdR-36U, which could contribute to the generation of mild CSF forms." (PMID 40006915, 2025). "Infection of HeLa cells with C. trachomatis serovar L2 (LGV-L2) led to an increase in ISG15 levels in a time- and dose-dependent manner, which correlated with an increase in ISG15 transcripts 6 h post-infection (hpi) and onwards." (PMID 39345209, 2024). "In the uninfected Day 0 samples, the naïve PBMCs which were not exposed to vaccine or infection showed a modest increase of ISG-15." (PMID 39065157, 2024). "By contrast, the overexpression of Ythdc2 could significantly inhibit the expression levels of interferon IFN1, TNF-α, Mx1, ISG15, and Viperin after SCRV infection." (PMID 38361078, 2024). "Upon SCRV infection, the overexpression of Linear-Flag-MORC3-84aa expression plasmids could significantly inhibit the expression levels of ISG15, Mx1 and Viperin." (PMID 38150467, 2023). "We observed a NS1 dosage-dependent host response for genes involved in the inflammatory response (IL-6, IFNB1) and interferon stimulation (IFIT1, MX1, ISG15), with the IAV-NS1-T infection generating an intermediate phenotype at both the transcript and at the protein levels." (PMID 37876781, 2023). "However, the results showed that knockdown of MORC3 can significantly enhance the expression levels of ISG15, Mx1, Viperin, and IFN1 upon SCRV infection." (PMID 38150467, 2023). "HIV-Luc IND116A infection of siNT control cells resulted in low but significant induction of ISG15, IFIT1, and IFIT2 compared to that in noninfected control cells." (PMID 37922361, 2023).
infection (continued). "Upon SCRV infection, MORC3 could significantly inhibit the expression levels of ISG15, Mx1, Viperin, and IFN1." (PMID 38150467, 2023). "We observed a large increase in both immunoproteasomal subunits PSMB8 and PSMB10, and the IFN-activated proteins ISG15 and MX1 in serum and in infected cells 3 and 7 days after infection, thus connecting these changes in blood proteins to those after SARS-CoV-2 infection." (PMID 37739942, 2023). "Interestingly, the mRNA levels of RIG-I, ISG15, and ISG56 were transiently upregulated 12 h after PAstV1 infection, while those of MDA5 were significantly elevated at 24 h." (PMID 37140381, 2023). "To further explore the function of PD-L1 in suppressing host antiviral responses to IAV infection, we analyzed the expression levels of innate immunity-related genes, including IFN-β, IL-29, ISG15, and MxA, in cells overexpressing PD-L1 during WSN or PR8 infection." (PMID 37239931, 2023). "To analyze whether ISG15 has a role in EV release, we evaluated the formation of comet-like plaques during IHD-J infection." (PMID 37036376, 2023). "Upon infection, this cluster enriched a strong interferon-stimulated gene (ISG) signature, including master antiviral regulators Irf7, Oas3, and Isg15, suggesting induction of the ISG program could occur in neutrophils under severe conditions." (PMID 35420442, 2022). "Western blotting analysis showed that compared with the mock-infected cells, both phosphorylated and non-phosphorylated forms of STAT1 as well as the expression of ISG15, were upregulated markedly in PEDV-infected cells, especially in the late stage of infection (18-24 hpi)." (PMID 35958569, 2022). "However, the constitutive elevation of ISG15 is noted in cancer, neurodegenerative diseases, upon TBI, and in response to pathogen infections." (PMID 35159348, 2022). "Upon Tha and Th2P-4M infection, foetal pAstrocytes strongly induced the expression of IFIH1, CCL5, and CXCL10, whereas hiMicros strongly upregulated expression of CXCL10 and genes coding for antiviral proteins ISG15 and MX1." (PMID 36680128, 2022). "However, other proteins such as ISG15, Nitric Oxide Synthase 2 (NOS2), IL1-β and IFIT1 were similarly altered in both conditions upon infection." (PMID 36131943, 2022). "Moreover, infection led to an upregulation of IFN signaling pathway-related genes and to the induction of Isg15 and Irf7." (PMID 35215832, 2022). "p62 knockdown significantly reduced levels of IRF7, ISG15, IFIT1, IFIT2, and IFIT3 genes, suggesting that p62 was required for maximal activation of the innate immune response during KSHV primary infection." (PMID 33414399, 2021). "Some of the genes that were similarly modulated by MR766 and Rio-U1 related to cytokine signaling (CXCL10/11, CCL8) and the IFN response (IFIT2, ISG15, OAS2, DDX58, among others), suggesting some degree of similarity in signaling patterns following infection with either virus." (PMID 33405202, 2021). "BAFT and ISG15 are involved in processes related to immune response, while DNMT1 is related to the preservation of methylation patterns, and its expression is modulated by pathogen infections." (PMID 33808774, 2021). "Contrary to SARS‐CoV‐2 infection, infection of IRF3 KO T84 cells by astrovirus did not impair IFN‐mediated signaling as a similar upregulation of ISG15 was observed in both mock‐infected and astrovirus‐infected cells upon IFN treatment." (PMID 33904651, 2021). "Infection with SFSV, however, also resulted in elevated levels of RIG-I, MxA, and ISG15 proteins." (PMID 34726591, 2021). "In response to R. equi infection, while STING KO macrophages induced Tnfa to comparable levels as control macrophages (expressing a GFP-targeting guide RNA), they failed to induce Ifnb, Isg15, or Ifit1 at 4- or 8h post-infection." (PMID 34473814, 2021). "Given that ISGs such as ISG15 and OASL were downregulated, we postulated that the JAK-STAT signaling cascade pathway might be influenced by the infection of oncoVV-WCL." (PMID 34064193, 2021).